EPO (erythropoietin)
Diseases named in the same sentence as EPO in open-access papers (continued):
Sharing a sentence is not in itself a finding about the gene and the disease.
breast carcinoma (continued). "On the other hand, Zhou at al. very recently reported that EPO promoted tumorigenesis by activating JAK/STAT signaling in breast tumor-initiating cells and that high levels of endogenous EPO gene expression correlated with shortened relapse-free survival in a mouse model of breast cancer." (PMID 28415825, 2017). "Similarly, high expression of EPO and its receptor, EPOR, has recently been described in breast cancer cells, and in regions of hypoxia in breast tumors, suggesting that this gene may be involved in breast tumorigenesis by promoting tissue hypoxia." (PMID 27708222, 2016). "In preclinical studies, EPO has been shown to induce the proliferation of different cancer cells, such as colorectal or breast cancer, and may stimulate the conversion of non-stem breast cancer cells into breast cancer-initiating cells." (PMID 36052260, 2022). "However, tumor sections revealed a negative correlation between serum erythropoietin levels and the number of ALDH1A3-positive cells, a marker for breast cancer-initiating cells." (PMID 30700319, 2019). "We confirmed EGR1, FOS and EPOR as transcription targets of the EPO-EPOR signaling loop, but could not correlate the expression of different EPOR isoforms with the invasiveness of breast cancer cell lines." (PMID 24294184, 2013). "In contrast to the well-established signaling pathway activation mediated by EPO-EPOR in hematopoietic cells, EPO treatment of mammary carcinoma cells did not induce the phosphorylation of the JAK2/STAT5 axis- a critical pathway for physiologic EPOR function in hematopoietic cells." (PMID 17579721, 2007). "The demonstration of the erythropoietin (EPO) receptor in various neoplastic tissues and the observation in a recent clinical trial that mortality was higher in nonanaemic rhEPO-treated breast cancer patients highlighted the possible effects of rhEPO on tumour growth and angiogenesis." (PMID 17299396, 2007). "In a non-hematopoietic myoblast-like cell line, EPO has been previously reported to induce the tyrosine phosphorylation of JAK1, however, rEPO did not induce the tyrosine phosphorylation of JAK1 in mammary carcinoma cells." (PMID 17579721, 2007).
red cell aplasia (49 papers, 2009 to 2025). "In this case, a chronic liver disease patient developed anti-erythropoietin associated pure red cell aplasia and recovered after liver transplantation and immunosuppression." (PMID 26240773, 2015). "A rare potential side effect of recombinant erythropoietin is anti-erythropoietin antibody associated pure red cell aplasia." (PMID 26240773, 2015). "However, since 1998, some severe adverse effects such as EPO-associated pure red cell aplasia by long-term EPO injection induced neutralizing antibodies have been reported." (PMID 29720275, 2018). "EPO antibodies were associated with the severe consequence of pure red cell aplasia." (PMID 27617228, 2016). "However, it was noted that the subcutaneous administration of EPO was associated with pure red cell aplasia (PRCA) in some cases, because of NAbs generated to endogenous EPO." (PMID 27437405, 2016). "Antibodies may also suppress erythropoietin-induced RBC production causing pure red-cell aplasia." (PMID 30347001, 2018). "A well-known example is the generation of nAb against therapeutic erythropoietin that interact and neutralize endogenous erythropoietin as well, leading to pure red cell aplasia." (PMID 40061940, 2025). "EPO-induced Pure Red Cell Aplasia (PRCA) is one of the very rare complications, with an incidence of 0.02–0.03 per 10,000 patient years." (PMID 38528249, 2024). "Transfusion independence (TI) was significantly effective in the roxadustat-treated group in pure red cell aplasia (PRCA) patients who resist to EPO (rHu-EPO) treatment due to antibodies against EPO, can also be improved by roxadustat." (PMID 36724056, 2023). "EPO aggregation has been reported that is critically connected to the immunochemistry of rhEPO preparation; it was specifically responsible for the development of EPO antibody-mediated deadly disease condition called pure red cell aplasia (PRCA)." (PMID 37631301, 2023). "Patients who were administered recombinant human erythropoietin developed anti-EPO antibodies, and eventually suffered from pure red cell aplasia." (PMID 36989322, 2023). "Anti‐erythropoietin antibody was present in high titre (> 1:260) and he was diagnosed with erythropoietin–induced pure red cell aplasia (PRCA)." (PMID 36051084, 2022). "Anti-erythropoietin (anti-EPO) antibody-mediated pure red cell aplasia (PRCA) is a rarely seen disease." (PMID 36524109, 2022). "The application of erythropoietin (EPO) can bring about a rare but serious complication called anti-EPO antibody-mediated pure red cell aplasia (PRCA)." (PMID 32856389, 2020). "The antibodies can cross neutralize these (endogenous) factors as has happened with epoetins, which induced neutralizing antibodies neutralizedto erythropoietin, essential for red blood cell maturation, leading to Pure Red Cell Aplasia (PRCA)." (PMID 31544827, 2019). "Pure red cell aplasia (PRCA) due to antibody productionagainst rHu-EPO is a rare but major complication of this drug." (PMID 28042550, 2017). "The original recombinant erythropoietin (EPO) drug (Epogen) was introduced in 1988 and has been used successfully worldwide; however, incidences of neutralising anti-EPO ADA have been reported with the development of pure red cell aplasia (PRCA)." (PMID 27191002, 2016). "Median delay between initiation of erythropoietin treatment and start of pure red cell aplasia was 11 months." (PMID 26240773, 2015). "Related to that, induction of antibodies against EPO molecule was observed in patients treated with recombinant human EPO which resulted in pure red cell aplasia." (PMID 23978045, 2013). "Between 1999 and 2002, following a manufacturing change, 206 patients treated with erythropoietin developed pure red cell aplasia (PRCA)." (PMID 21203556, 2010). "Most importantly, it has eliminated the need for transfusions in patients with anti-erythropoietin antibody-mediated pure red cell aplasia." (PMID 19143750, 2009).
red cell aplasia (continued). "The co-occurrence of ‘ESAs’, ‘anti-erythropoietin antibody’ and ‘pure red cell aplasia (PRCA)’ in the keyword cluster #7 analysis indicates antibody-mediated ESA risk, although this rare but serious complication is mainly caused by subcutaneous ESA administration." (PMID 41188188, 2025). "EPO antibodies mediate pure red cell aplasia after treatment with recombinant EPO products." (PMID 39502472, 2024). "This is shown by an incident in Europe involving the production of neutralizing antibodies that cross-reacted with intrinsic erythropoietin, resulting in pure red cell aplasia in approximately 200 patients treated with various epoetin alfa and epoetin beta preparations between 1998 and 2003." (PMID 36559215, 2022). "In addition, EPO antibodies have been demonstrated to mediate pure red cell aplasia after treatment with recombinant EPO products." (PMID 32318578, 2020). "In conclusion, anti-erythropoietin associated pure red cell aplasia is a serious complication of erythropoietin therapy, but this entity should not be considered a contraindication for solid organ transplantation." (PMID 26240773, 2015). "The patient was felt to have pure red cell aplasia due to anti-erythropoietin antibodies." (PMID 26240773, 2015). "The diagnosis of pure red cell aplasia from anti-epoetin antibodies should be considered in patients undergoing therapy for chronic hepatitis C virus infection who develop severe anemia after administration of erythropoietin or darbepoetin." (PMID 19830190, 2009). "However, a long-term application of exogenous EPO may activate specific T cells, and thus stimulate the neutralizing ADAs that cross-react with endogenous EPO, leading to pure red cell aplasia consequently." (PMID 38105750, 2023). "In addition, previously reported cases of the life threatening pure red cell aplasia might encourage the use of brand name based listing for EPO whether for the R-BMP or the BSPs." (PMID 28871421, 2017). "Examples include red cell aplasia, where EPC fail to grow in the presence of EPO, and polycythemia vera where they can grow in the absence of EPO." (PMID 31810354, 2019). "The rare condition called pure red cell aplasia (PRCA) has been detected with subcutaneous injections and poor packaging of the EPO medicine." (PMID 29673379, 2018). "The rare condition, pure red cell aplasia (PRCA), has been detected with subcutaneous infusions and poor packaging of the EPO medication." (PMID 30400939, 2018). "Pure red cell aplasia (PRCA) is more common after viral infections, such as in the setting of Parvovirus B19 due to an immunological response against erythropoietin or red cell precursors." (PMID 27073704, 2016). "There were no signs of pure red cell aplasia in the patient’s bone marrow and serum erythropoietin remained detectable and reticulocytes were normal at the last available measurement." (PMID 29895954, 2018). "Pure red cell aplasia was ruled out by a high number of reticulocytes and the absence of anti-erythropoietin (EPO) antibody and anti-EPO receptor antibody using a commercial radioimmunoprecipitation assay." (PMID 29047386, 2017). "LIPS readily detected anti-EPO autoantibodies in serum samples from subjects with presumptive pure red cell aplasia but not in any of the samples from HIV-infected or uninfected individuals." (PMID 26599070, 2015). "Epoetin delta was well tolerated for the duration of the study and no patient developed anti-erythropoietin antibodies or pure red cell aplasia." (PMID 19243619, 2009). "During the 52 weeks of this trial no patient developed anti-erythropoietin antibodies or pure red cell aplasia." (PMID 19243619, 2009). "Finally, there were no other cases of absolute or partial contraindication of EPO (e.g., pure red cell aplasia and documented hypersensitivity reactions to EPO) in the study population." (PMID 38029231, 2023).
red cell aplasia (continued). "Therefore, any potential antibody formed to Hematide is not likely to cross-react with erythropoietin and induce pure red cell aplasia." (PMID 19143750, 2009).
ischemic stroke (47 papers, 2009 to 2026). A stroke disorder caused by obstruction of blood flow to the brain, due to thrombotic (local blood clot formation) or embolic (due to a blood clot or other material traveling from another site) event. "Because parenchymal destruction in ischemic stroke tissue likely causes underestimation of absolute mRNA counts, we evaluated the EPO to hS3 expression ratio as a more reliable measure of relative expression dynamics." (PMID 41602576, 2026). "A study reported that an increase in serum EPO levels after ischemic stroke was associated with a favorable outcome." (PMID 32733466, 2020). "Erythropoietin (EPO) enhances the circulating level of endothelial progenitor cells (EPCs), which has been reported to be associated with prognostic outcome in ischemic stroke (IS) patients." (PMID 21269484, 2011). "And elevated blood pressure was prevalent in the acute period of ischemic stroke, activating the renin–angiotensin–aldosterone system and in turn causing the production of angiotensin‐2, vasoconstriction, and erythropoietin." (PMID 33943024, 2021). "In conclusion, we suggest that MK-X might be used as a novel drug for protection from brain injury caused by ischemic stroke, which penetrates into the brain faster in comparison with EPO, even though MK-X and EPO have similar protective effects against excitotoxicity." (PMID 28817120, 2017). "In neurological diseases, EPO is induced under hypoxic conditions, e.g., ischemic stroke, and inflammatory conditions, e.g., experimental autoimmune encephalomyelitis (EAE)." (PMID 41602576, 2026). "As expected, EPO mRNA expression is scarce, showing upregulation in ischemic stroke and downregulation in neurodegenerative diseases." (PMID 41602576, 2026). "The evidence indicates that the therapeutic effect is exerted via the HIF-1α/EPO/VEGFA signaling pathway with regard to ischemic stroke." (PMID 40166460, 2025). "These beneficial effects of EPO are of interest concerning the potential therapy or recovery after an ischemic stroke." (PMID 39355466, 2024). "Recombinant human EPO produced in mammalian cells (rhuEPOM) has been demonstrated to display remarkable neuroprotection in animal models of ischemic stroke." (PMID 37111367, 2023). "In 2016, another clinical study proved the combination therapeutic effects of EPO and granulocyte colony-stimulating factor in ischemic stroke patients." (PMID 35250554, 2022). "We wish to provide valuable information on EPO and EPO derivatives’ treatment for ischemic stroke for basic researchers and clinicians to accelerate the process of their clinical applications." (PMID 35250554, 2022). "After ischemic stroke, EPO and EPORs were upregulated and involved in protecting ischemic neurons and promoting tissue regeneration." (PMID 35250554, 2022). "Both of these effects were suppressed after EPO administration, providing further insight into the anti-apoptotic/pyroptotic and anti-inflammatory effects of EPO after ischemic stroke." (PMID 34628598, 2022). "The intracerebral transplantation of EPO‐producing fibroblasts benefited an ischemic stroke model probably via the enhancement of neurogenesis." (PMID 30920178, 2019). "While the use of EPO as single-agent therapy after ischemic stroke appears to be safe, the innocuousness of the PERK inhibitor GSK-2606414 has yet to be evaluated pre-clinically." (PMID 31683519, 2019). "For clinical application of EPO for ischemic injury, a Phase I clinical trial for EPO treatment of ischemic stroke provided evidence for the safety and potential efficacy showing an association with improvement in clinical outcome at 1 month." (PMID 32038269, 2019). "Recently, EPO has been shown to enhance endogenous neurogenesis and improve functional recovery in a rodent model of ischemic stroke." (PMID 30920178, 2019). "To visualize Xbp1s PCR products after ischemic stroke and upon EPO treatment, we performed an Xbp1s splicing detection assay." (PMID 31683519, 2019).
ischemic stroke (continued). "We found earlier and larger infarct demarcations in Grina−/− mice compared to wildtype mice, which was accompanied by a worse neurological outcome and an abolishment of EPO-mediated neuroprotection after ischemic stroke." (PMID 31683519, 2019). "Other possible reasons for ischemic stroke include erythropoietin-induced thromboembolic events, arteriovenous shunt-related steal-like influence, and hypotensive effect during the ultra-filtration stage of hemodialysis." (PMID 29329323, 2018). "This study provides a novel insight into EPO treatment for ischemic stroke and explores EPO’s effects on microglial polarization." (PMID 28840056, 2017). "We found that EPO treatment significantly reduced motor deficits after ischemic stroke as demonstrated by an increased latency to fall off the rotarod at 3 and 7 days post-injury (both P<0.05)." (PMID 28840056, 2017). "We found that MK-X administration with reperfusion dramatically reduced brain injury in an in vivo mouse model of ischemic stroke induced by middle cerebral artery occlusion, whereas EPO had little effect." (PMID 28817120, 2017). "Encouraging neuroprotective effects were reported in mouse models of ischemic stroke following administration of erythropoietin (EPO)." (PMID 27248662, 2016). "Here, we observed neuroprotective effects following sub-acute recombinant human EPO (rhEPO) administration in an ischemic stroke model based on platelet-rich thrombus formation, using chimeric 5- (i.e. young) and 20- (i.e. aged) months old mice." (PMID 27248662, 2016). "Our study revealed a neuroprotective role for EPO, through its anti-inflammatory properties, in the context of ischemic stroke induced by a platelet-rich thrombus." (PMID 27248662, 2016). "In a rat model of ischemic stroke, direct infusion of EPO in brain was neuroprotective and improved performance in the Morris water maze." (PMID 22567318, 2012). "Correspondingly, EPO treatment after ischemic stroke resulting in improved functional recovery induces BDNF and VEGF." (PMID 22567318, 2012). "Although low doses of EPO are associated with an increased risk of ischemic stroke, the association is not dose dependent." (PMID 41244199, 2025). "The adjunctive use of erythropoietin (EPO) with the MBH procedure has been reported to decrease the incidence of long-term cerebrovascular events in MMS patients following either hemorrhagic or ischemic stroke." (PMID 41154172, 2025). "A parallel could be drawn with a study in adults suffering from ischemic stroke, where those treated with high doses of erythropoietin experienced a higher mortality rate; however, the study could not pinpoint a singular cause for this outcome." (PMID 38804373, 2024). "So far, all angiogenic effects of EPO are induced after an ischemic stroke." (PMID 39355466, 2024). "Few studies provided comprehensive and latest knowledge of EPO treatment for ischemic stroke." (PMID 35250554, 2022). "The reperfusion time points addressed in this study were chosen to investigate the anti-inflammatory capacities of EPO in the acute and subacute phase after ischemic stroke and to allow potential comparisons with our previous data and several (pre)clinical studies." (PMID 34628598, 2022). "A thorough investigation of EPO derivatives is awaited to help yield enhanced understanding of their therapeutic mechanism and develop the potential novel therapeutic strategies for ischemic stroke." (PMID 35250554, 2022). "To investigate the impact of EPO and the depletion of Mi/MΦ TAK1 on gene expression of the inflammasomes as well as their associated downstream cascade after an ischemic stroke, we utilized brain biopsies from the periinfarct-zone of both genotypes after 6 and 72 h of reperfusion." (PMID 34628598, 2022). "However, the mechanism of EPO-induced neuroprotection in ischemic stroke remains vague, and further studies are warranted." (PMID 35250554, 2022).